HPN (hepsin)
Diseases named in the same sentence as HPN in open-access papers (continued):
Sharing a sentence is not in itself a finding about the gene and the disease.
cancer (44 papers, 2004 to 2025). A tumor composed of atypical neoplastic, often pleomorphic cells that invade other tissues. "Hepsin is a TTSP whose expression has been linked to greater tumorigenicity in different types of cancer, such as breast, lung, prostate and gastric cancer." (PMID 37275957, 2023). "HGF secreted as inactive zymogen (pro-HGF) from cancer associated stromal fibroblasts, and the proteolytic activation by several TTSPs including matriptase and hepsin is required." (PMID 32290402, 2020). "Curiously, low expression of hepsin is associated with poor survival in different cancer types, and transgenic overexpression of hepsin leads to loss of viability in various cancer cell lines." (PMID 31399560, 2019). "Hepsin, a membrane-associated serine protease, is frequently upregulated in epithelial cancers and involved in cancer progression." (PMID 27841306, 2016). "Among the altered TME, HPN, which has been associated with the growth and progression of various cancers, might partly account for the A allele carriers association with HCC susceptibility and prognosis." (PMID 35164791, 2022). "Another serine protease, Hepsin is overexpressed in several cancers including ovarian cancer, but its specific role remains to be elucidated." (PMID 40558552, 2025). "We examined the functional effects of hepsin expression on colon tumor cell proliferation, migration, invasion, activation of key cancer signaling proteins and plasma thrombin generation." (PMID 37275957, 2023). "Hepsin is a TTSP that exerts a complex influence on different types of cancer, parallel to the activation of the hemostatic system, and comprises critical nodes where multiple signaling pathways converge with coagulation cascade effectors." (PMID 37275957, 2023). "In cancers, for example, TTSPs, such as matriptase, matriptase-2, hepsin, and TMPRSS13, promote cancer progress by degrading extracellular matrix proteins and activating signaling pathways." (PMID 37509434, 2023). "In breast cancers, hepsin-mediated cleavage of fibronectin in the extracellular matrix has been identified as a key mechanism in transforming growth factor-beta signaling and cancer progression." (PMID 37509434, 2023). "It has been described that hepsin activates extracellular ligands that promote cancer progression, such as hepatocyte-growth factor." (PMID 37275957, 2023). "By deeply mining the TCGA datasets with hundreds or even thousands of samples, we found that hepsin was differentially expressed in 33 types of cancer." (PMID 35204704, 2022). "Among the altered TME, hepsin (HPN), which has been associated with the growth and progression of of various cancers, showed the most significant alteration in our discovery cohort." (PMID 35164791, 2022). "Biological functional studies have demonstrated oncogenic roles for hepsin in the regulation of cancer cell proliferation, invasion, migration, and metastasis, in in vitro and in vivo model systems." (PMID 35204704, 2022). "Additional analysis also showed that hepsin expression levels were much higher in renal and colorectal metastatic cancers in comparison with their primary cancers." (PMID 35204704, 2022). "As hepsin belongs to the transmembrane type II serine protease superfamily and has also been related with different malignant tumors, we performed a similar study to evaluate the interaction between hepsin and native or prelatent AT." (PMID 34067120, 2021). "To examine the intensity differences, we further analyzed the immunostaining scoring with H-score, and found that the expression level of HPN was significantly enhanced in cancer tissues." (PMID 33032611, 2020). "We found that HPN was highly expressed in cancer tissues compared with normal prostate, and the staining intensities seemed to vary between the cancer tissues with different pathology grading." (PMID 33032611, 2020).
cancer (continued). "Due to its overexpression, extracellular proteolytic activity, and functional involvement in basement membrane degradation and invasive tumor growth, hepsin was declared as a promising and druggable cancer target." (PMID 31399560, 2019). "The hepsin paradox describes reduced expression of hepsin in advanced PCa and other solid tumors and absence in metastasis-derived cancer cell lines, as well as adverse effects during transgenic overexpression." (PMID 31399560, 2019). "Comparatively weak expression levels of hepsin seem sufficient for the execution of at least some of its cancer-promoting effects, favoring oncogenic signaling, and stemness in PC3L1-HPN cells." (PMID 31399560, 2019). "In their study, absent or low hepsin immunostaining was dominant in benign samples, whereas hepsin staining was strong in cancer samples." (PMID 26014348, 2015). "Disruption of this structure is necessary for a local invasion in the early metastasis process.The molecular mechanisms involving hepsin in the progress of malignant neoplasm has become clear." (PMID 22649671, 2011). "Three separate studies identified hepsin as a significant cancer biomarker that can be used for cancer diagnosis." (PMID 15469618, 2004). "Despite a role in mediating cancer formation and progression, sosme reports suggest that high levels of Hepsin could have antitumor effects by reducing oncogenic signaling and increasing autophagy." (PMID 40558552, 2025). "HPN, hepsin, has frequently over-expressed in many cancers but is decreased in HCC cells." (PMID 38992651, 2024). "In addition to the liver, hepsin is expressed in the kidney, stomach, thyroid, pancreas, inner ear, and many types of cancers." (PMID 37509434, 2023). "Curiously, hepsin effects in cancer are not only tumorigenic, but its role is multifaceted." (PMID 37275957, 2023). "The specific enzymatic activity of hepsin promotes cell motility and cancer cell metastasis." (PMID 35204704, 2022). "Moreover, to further explore the regulation of immune molecules by HPN, correlation between HPN expression and 28 tumor-infiltrating lymphocytes (TILs) was analyzed across human heterogeneous cancers in the TISIDB database." (PMID 35164791, 2022). "The interaction between HPN and coagulation in this type of cancer could be explained by the ability of HPN to activate proteins, such as factor VII, XII and IX of the coagulation cascade, although none of these studies have been conducted in humans." (PMID 35804878, 2022). "In cancer, overexpression of hepsin mRNA is reported in prostate, ovary, kidney, and breast." (PMID 32290402, 2020). "In addition, the expression level of HPN in cancer tissues with high pathology grading (Gleason score = 7, 8, 9) was significantly higher than that with low pathology grading (Gleason score = 6)." (PMID 33032611, 2020). "At higher expression levels, excess hepsin activity becomes a burden for the cancer cell." (PMID 31399560, 2019). "ER stress and enhanced autophagy in response to hepsin overexpression were not limited to the PC-3 cell line with all its cancer-specific peculiarities, but also occurred in AR-positive LNCaP PCa and in HEK293 cells, which demonstrates generalizability of our findings." (PMID 31399560, 2019). "Yet among cancer samples, absent or low hepsin expression was associated with prostate-specific antigen (PSA) elevation after radical prostatectomy and large tumor size, indicating poorer survival." (PMID 26014348, 2015). "Molecular changes which may influence hypercoagulability include the expression of tissue factor (TF) as well as the proteases hepsin and cancer procoagulant by circulating tumour cells." (PMID 15913454, 2005). "The oncogenic functions of hepsin are mainly linked to proteolytic activities that disrupt epithelial integrity, and it regulatorily interacts with cell-proliferation, EMT/metastasis, inflammatory, and tyrosine-kinase-signaling pathways, promoting cancer cell motility and metastasis." (PMID 35204704, 2022).
cancer (continued). "Thus, the effect of HPN on carcinogenesis might be tissue- and cell type-specific, which may explain the conflicting literature on the influence of HPN in different cancer cells." (PMID 35164791, 2022). "Likewise, the role of the TTSP in tumour growth, cancer invasion and metastasis processes are being increasingly documented for proteases such as matriptase, matriptase-2 and hepsin." (PMID 17579619, 2007). "SRI31215, a small molecule that acts as a triplex inhibitor of hepatocyte growth factor activator (HGFA), matriptase, and hepsin has been reported to inhibit EMT and migration of cancer cells." (PMID 31292507, 2019). "Activation of pro-HGF is primarily driven by matriptase, hepsin and HGFA, serine proteases that are commonly overexpressed in cancer tissues." (PMID 27121052, 2016). "Hepsin, (also called TMPRSS1) and TMPRSS3 are type II transmembrane serine proteases (TTSPs) that are involved in cancer progression." (PMID 26014348, 2015). "GREAT also reported that HepG2-enriched windows were close to many cancer genes HPX, HPN, LCAT, TST, GSTM1, CEPBA, CYP2B6." (PMID 25522020, 2014). "Like Hepsin, HOXB13 expression was overall significantly elevated in cancer tissue, although the increase was highly variable." (PMID 17280610, 2007). "The study demonstrates a role for hepsin as a regulator of cell proliferation and tumor growth through TGFβ and EGFR pathways, warranting consideration of hepsin as a potential indirect upstream target for therapeutic inhibition of TGFβ and EGFR pathways in cancer." (PMID 37872868, 2023).
tumor (29 papers, 2004 to 2025). "The suppression of tumor growth upon loss of hepsin was accompanied by downregulation of TGFβ and EGFR signaling together with a reduction in epidermal growth factor receptor (EGFR) protein levels." (PMID 37872868, 2023). "In this study, we investigated the association of plasma hepsin levels with tumor stage and thrombosis in CRC patients." (PMID 37275957, 2023). "In conclusion, our results demonstrated that high hepsin levels are associated to a more aggressive tumor phenotype because of the higher potential for invasion of CRC cells and greater activation of coagulation." (PMID 37275957, 2023). "Among metastatic patients, low hepsin expression was associated with a low degree of tumor differentiation (p-value < 0.001) and with major metastatic dissemination (p-value = 0.023)." (PMID 35804878, 2022). "In clinical non-tumor liver tissues, hepsin levels were positively associated with C3 expression, which strongly suggests that hepsin is required for C3 production in normal liver." (PMID 26760961, 2016). "In vitro and in vivo studies showed enhanced hepsin expression in breast cancer tissues, which is associated with tumour growth and progression." (PMID 25598217, 2015). "In order to better understand the role of hepsin in these processes, it would help to review how the associated membrane proteolysis participates in the tumor’s progress." (PMID 22649671, 2011). "Our results support the hypothesis that a high expression of HPN in the tumor triples the risk of recurrence after surgery for localized CRC, being a better prognostic factor than other classic histopathological factors." (PMID 35804878, 2022). "Furthermore, in patients with localized disease, increased expression of HPN compared to patients with low staining raises thrombotic risk, independently of tumor recurrence." (PMID 35804878, 2022). "Hepsin may also directly contribute to tumor progression and metastasis by causing defects in cell junctions." (PMID 26014348, 2015). "Hepsin is involved in such phenomena as the increase in cell motility, matrix protein separation and extracellular structure disorganization, and activation of extracellular proteases and their cascades, which underlie tumor progression." (PMID 22649671, 2011). "These significant correlations between HPN expression and marker genes from immune cells like tumor-infiltrating monocytes, M2 macrophages, dendritic cells and T-helper cells suggests that HPN in A allele-related HCC might be involved in the regulation of tumor immune infiltration in HCC." (PMID 35164791, 2022). "On average, there was a significant increase in the total hPn mRNA expression in tumor tissue, when compared to NAT." (PMID 39334860, 2024). "Expression levels varied for the serine proteases with an increase in tumor mRNA levels for HPN and HGFA, while ST14 was downregulated in tumor samples." (PMID 38212428, 2024). "Hepsin has an extracellular fraction that can be released from the transmembrane region of tumor cells." (PMID 37275957, 2023). "Discussion: Our results demonstrate that hepsin overexpression correlates with a more aggressive and prothrombotic tumor phenotype." (PMID 37275957, 2023). "Recently, we identified hepsin from primary tumor as a prognostic marker for metastasis and thrombosis in patients with localized tumors." (PMID 37275957, 2023). "Hepsin is a serine protease whose deregulation leads to tumor invasion and metastasis in many tumor types." (PMID 35804878, 2022). "The lower expression of HPN in peritumor tissues and tumor tissues of HCC patients indicate a protective role for HPN in HCC occurrence." (PMID 35164791, 2022). "Hepsin is a type II transmembrane serine protease whose deregulation promotes tumor invasion by proteolysis of the pericellular components." (PMID 35804878, 2022). "During overexpression of hepsin in tumor cell lines, adverse effects such as growth suppression, increased cell death, and reduction of invasive growth were observed." (PMID 31399560, 2019).
tumor (continued). "Based on these data, researchers coined the term “hepsin-paradox”, which describes the importance of a precise temporal and spatial restriction of hepsin overexpression for the tumor in order to avoid adverse effects." (PMID 31399560, 2019). "We found that N-glycosylation at Asn-112 is important for hepsin cell surface targeting and tumor invasion and migration." (PMID 27841306, 2016). "Previous study revealed that the expression levels of hepsin in non-tumor liver tissues are higher than those in the corresponding HCC tissues." (PMID 26760961, 2016). "The predictors included tumor T stage, N stage, M stage and hepsin expression, all of which were independent prognostic indicators for OS." (PMID 27841306, 2016). "Consistent with this, our clinical HCC tissues exhibited decreased hepsin expression in comparison to matched non-tumor liver tissues." (PMID 26760961, 2016). "Abnormal activation of the HGF/c-Met signaling pathway by aberrant hepsin overexpression is a possible mechanism for the enhancement of tumor progression." (PMID 26014348, 2015). "The finding that testisin and hepsin enzymatic activities can be targeted on tumor cells by PrAg-PCIS suggests that the membrane-anchored serine proteases constitute viable targets for engineered anthrax toxins." (PMID 26392335, 2015). "As previously stated, the expression level of hepsin (limited in a normal cell) rapidly increases in a progressing tumor." (PMID 22649671, 2011). "It is necessary to note that the specificity of high expression levels of hepsin by tumor cells had attracted attention at the earliest stages of the study of that protein." (PMID 22649671, 2011). "Serine protease hepsin is one of the enzymes that regulate the process of local invasion of tumor cells." (PMID 22649671, 2011). "Hepsin was shown to be the key activation factor of the proteolytic processes in tumor tissue, which result in dissemination of tumor cells." (PMID 22649671, 2011). "Hepsin, a protease found on hepatocyte surface membranes but also in several tumour cell lines, has been shown to initiate coagulation by activating factor VIIa independent of TF." (PMID 15913454, 2005). "Brief literature search in PubMed showed that hepsin is a well-characterized transmembrane protease that is expressed at high level in tumor." (PMID 15469618, 2004). "In 10 out of 11 cases, total hPn mRNA expression was up-regulated in tumor tissue, compared to NAT." (PMID 39334860, 2024). "However, how exactly active hepsin promotes cell proliferation machinery to sustain tumor growth is not fully understood." (PMID 37872868, 2023). "In addition to its multifaceted tumor effect, hepsin has another peculiarity—it activates coagulation factor VII, which initiates the extrinsic coagulation cascade." (PMID 37275957, 2023). "Since the important role of HPN in the immune system and the quantity and activity status of tumor-infiltrating lymphocytes can influence the prognosis of HCC patients, the correlation of HPN expression with markers of different subsets of immune cells in our data set was next analyzed." (PMID 35164791, 2022). "Therefore, our results showed that high expression of HPN contributed to achieving moderate tumor differentiation." (PMID 35804878, 2022). "In addition, a small-molecule inhibitor of uPA, WX-UK1, has also shown anti-tumor and anti-metastatic activity via downregulating hepsin expression." (PMID 35204704, 2022). "Our study provides a new potential mechanism by which HPN may play an important role in A allele carriers for HCC susceptibility and prognosis through tumor immune infiltration." (PMID 35164791, 2022). "The current study is a preliminary part of a larger study, validation of the POR polymorphism-related HCC risk and prognosis in additional larger HCC cohorts, and the exact detailed mechanism by which HPN regulates tumor infiltration of immune cells in HCC are needed to verify our results." (PMID 35164791, 2022).